SMIM21 (small integral membrane protein 21)
Synonyms: C18orf62
Tractability: Antibody: UniProt predicts a signal peptide or a membrane-spanning region.
Gene: Protein-coding gene on chromosome 18 (75,409,476 to 75,427,703, reverse strand). Ensembl gene ENSG00000206026.
Subcellular location: Membrane
Gene Ontology:
Molecular function: protein binding
Cellular component: membrane
Genetic constraint (gnomAD): Loss-of-function variants: 7 observed, 7.71 expected, observed/expected ratio (o/e) 0.91, 90% interval 0.51 to 1.65. That is too few expected variants to judge how well the gene tolerates losing a copy. Missense variants: 102 observed, 96.23 expected, observed/expected ratio (o/e) 1.06, 90% interval 0.9 to 1.25. Synonymous variants: 27 observed, 33 expected, observed/expected ratio (o/e) 0.82, 90% interval 0.6 to 1.13.
Homologues: Orthologues: chimpanzee SMIM21 (96% identical).